IFNG (interferon gamma)
Diseases named in the same sentence as IFNG in open-access papers (continued):
Sharing a sentence is not in itself a finding about the gene and the disease.
AIDS (85 papers, 1995 to 2025). A syndrome resulting from the acquired deficiency of cellular immunity caused by the human immunodeficiency virus (HIV). "Neutralizing anti-IFNγ autoantibodies disrupting IFNγ signalling have been identified as the cause of a severe and unique acquired immunodeficiency syndrome with increased susceptibility to NTM and other intracellular pathogens." (PMID 33176707, 2020). "In 2004, high-titer neutralizing autoantibodies against IFNγ were first identified as the cause of an acquired immunodeficiency syndrome subsequently termed adult-onset immunodeficiency with anti-interferon-gamma autoantibodies (AIIA)." (PMID 33176707, 2020). "The aim of this study was to compare the characteristics and mortality associated with talaromycosis in adult immunocompromised individuals caused by the anti-interferon-gamma autoantibody (anti-IFN- γ AAb) with those of people living with HIV/AIDS (PWHA)." (PMID 40344159, 2025). "When therapy is delayed, the chronic immune activation and profound immunosuppression linked to HIV infection progression towards AIDS, with a reduced number of interferon-gamma-producing HBV-specific CD8+ T cells, can increase the risk of severe evolution." (PMID 37238976, 2023). "Significantly enhanced susceptibility to TB in people suffering from HIV/AIDS or inherited IFNγ deficiencies underlines the critical role of IFNγ-producing CD4+ T cells (IFNγ+CD4+ T cells) in host resistance to Mtb." (PMID 28646367, 2017). "It has been suggested that individuals with the homozygous IFNγ-874A/A genotype have a significantly higher risk of infection and progression to AIDS, similar to the results found here." (PMID 25802474, 2015). "There is strong evidence that lack of CD4+IFNγ+ T cells or IFNγ signaling, as seen in advanced AIDS patients and individuals with genetic mutations of various components IFNγ-IL-12 axis, respectively are vulnerable to TB and non-tuberculous mycobacterial infections." (PMID 39717773, 2024). "Initially produced to clear the primary infection, IFNγ together with other inflammatory cytokines are involved in establishing a chronic immune activation that exacerbates clinical diseases associated with AIDS." (PMID 24454311, 2014). "There is a conflicting view regarding the role of cytokines such as IFNγ in modulating cellular immunity which can in turn determine the viral set point, as a high viral set point is positively associated with progression to AIDS." (PMID 24454311, 2014). "The importance of IL-12 in human CM was shown by (a) a correlation between higher CSF levels of IL-12 cytokine and increased survival in AIDS patients with CM, and (b) an increased ability to produce IFNγ when human PBMCs were treated with IL-12." (PMID 29333430, 2017). "The use of IFNγ as cytokine adjuvant for HIV-1 vaccines has been studied more extensively in animal models of AIDS than in humans." (PMID 24454311, 2014). "Based on these observations, clinical trials in adult patients have evaluated the toxicity, pharmacokinetics, and therapeutic effect of IFNγ on HIV-1 p24 load, AIDS-associated complex (ARC), and AIDS-associated Kaposi’s sarcoma (KS)." (PMID 24454311, 2014). "The difficulty in correlating serum IFNγ levels with HIV/AIDS clinical status has been attributed to the role that IFNγ plays as an inflammatory cytokine as well as a cytokine that enhances antiviral immunity." (PMID 24454311, 2014). "Our study has potential implications in relation to the reduction of IFNγ levels seen in HIV infection and the high susceptibility of Africans living with HIV/AIDS to NTS bacteremia." (PMID 21048923, 2010). "According to this theory, immune activation (following an infection such as HIV/AIDS) releases pro-inflammatory cytokines such as interferon gamma (IFNγ), interleukin 6 (IL-6), and tumor necrosis factor alpha (TNF-α) which induce secretion of indoleamine 2, 3-dioxygenase (IDO)." (PMID 29298663, 2018).
AIDS (continued). "Interferon-γ (IFNγ) plays various roles in the pathogenesis of HIV/AIDS." (PMID 24454311, 2014). "This reduction in IFNγ levels could, at least in part, account for the strong clinical association between invasive NTS disease and HIV/AIDS in Africa." (PMID 21048923, 2010). "One year after seroconversion, neither the absolute number of single IFNγ producing, nor of single IL-2 producing nor of double IFNγ+IL-2 producing Gag-specific CD8+ T cells were significantly associated with AIDS-free survival time." (PMID 18648514, 2008). "One host factor suggested to be involved is a defective interferon-gamma (IFN-γ) response, as evidenced by disseminated MAC disease in cases possessing a genetic mutation of the IFN-γ receptor or autoantibodies to IFN-γ in non- acquired immunodeficiency disease syndrome (AIDS) patients." (PMID 37009882, 2023). "The inability of IFNγ to enhance the vaccine efficacy may be attributed to the fact that AIDS lentiviral proteins themselves can induce IFNγ production in T cells as observed in animals vaccinated with viral protein or inactivated virus in conventional adjuvant." (PMID 24454311, 2014). "Kaplan-Meier survival analysis and Cox proportional hazard models showed that frequencies of cytokine-producing Gag-specific CD8+ T cells (IFNγ, IL-2 or both) shortly after seroconversion were neither associated with time to AIDS nor with the rate of CD4+ T-cell decline." (PMID 18648514, 2008). "In individuals with advanced HIV/AIDS, latent tissue cysts of Toxoplasma reactivate because of severe depletion of CD4+ T cells and consequent impairment of IL-12 and IFNγ immune surveillance." (PMID 40559542, 2025). "Previous reports have also shown that PKC modulators can affect NK cell functions, including activation, cytotoxicity, antibody-dependent cellular cytotoxicity (ADCC), and secretion of interferon-gamma (IFNγ), an important pro-inflammatory cytokine involved in the pathogenesis of HIV/AIDS." (PMID 38765786, 2024). "In subsequent functional experiments, we found that ZNF683 increased the proliferation and IFNγ secretion ability of CD8+ T cells, thus decreasing SIV or HIV replication, which may be related to AIDS progression in SIVmac239-infected NPMs." (PMID 35458449, 2022). "However, at the time of CM-IRIS, there are significant increases in CSF levels of IFNγ, TNFα, G-CSF, VEGF and eotaxin compared to baseline levels within AIDS patients." (PMID 29333430, 2017). "In a study performed over 25 years ago, no people with AIDS who received IFNγ therapy developed S. aureus bacteremia or nonbacteremic infections, compared to 5 of 52 who received IL-2." (PMID 27093273, 2016). "Remarkably, IFNγ responses were consistently detected in both CD3+CD4+ and CD3+CD8+ T cells of the HIV+ subjects at various clinical stages, but IFNγ responses alone had no direct correlation to delay in progression to AIDS." (PMID 24454311, 2014). "Expansion of non-CD4-expressing cells of the innate immune system with IFNγ-producing capacity, in particular NK cells and γδ-T cells, could compensate for lost IFNγ production by CD4+-T cells, particularly in advanced HIV/AIDS." (PMID 21048923, 2010). "The activation of macrophages and inhibition of MAC growth depends on its strain; for instance, interferon-gamma (IFN-γ) facilitates the inhibition of certain non-AIDS strains of MAC, but not some isolates from patients with AIDS." (PMID 31516884, 2018). "Notably, in comparison to the potent anti-HIV and -KS activities of IFNα and β, the lack of anti-HIV/AIDS activities of IFNγ greatly reduced the enthusiasm toward IFNγ and therapeutic focus shifted to IFNα as therapy against HIV/AIDS." (PMID 24454311, 2014).
dermatitis (85 papers, 2012 to 2025). An inflammatory process affecting the skin. "iNOS is expressed in response to lipopolysaccharide (LPS), interferon-gamma (IFN-γ), etc.; biosynthesizes NO; and is known to be involved in causing skin erythema, dermatosis, and an inflammatory response, as well as in regulating immune function." (PMID 36557931, 2022). "Jaungo showed anti-inflammatory and skin regeneration effects by reducing Immunoglobulin E (IgE), thymus and activation-regulated chemokine (TARC), and interferon-gamma (IFNγ) and inhibiting production of eotaxin for dermatitis." (PMID 37469863, 2023). "The results of the present study indicated that LOC has anti-inflammatory and antiatopic dermatitis effects via various molecular targets by directly or indirectly acting on signalling pathways stimulated by TNFα/IFNγ." (PMID 34795780, 2021). "Based on these observations, we hypothesised that, during infection, Vγ6+ cells expand in the skin and are important for driving subcutaneous adipose tissue wasting, limiting IFNγ-driven skin inflammation, and controlling parasite burden." (PMID 37644007, 2023). "Lastly, we hypothesised that loss of Vγ4+ and Vγ6+ cells may lead to an increased frequency of IFNγ+ T cells, which could explain the increased skin inflammation that we observed during infection." (PMID 37644007, 2023). "In contrast, the downregulation of interferon gamma (IFN-γ) in T helper (Th) 1-dominant skin disorders may lead to more adverse events, given the crucial role of IFN-γ in antiviral and antitumoral immunity." (PMID 35967358, 2022). "Xiao-feng-san might also correct the Th1/Th2 balance by preventing the increase in interleukin-4 mRNA expression and the decrease in interferon-gamma mRNA expression to inhibit dermatitis." (PMID 27822287, 2016). "It have been reported that other herbal medicine containing astragalus have anti-inflammatory activity through decreasing inflammation related cytokine, Tumor Necrosis Factor (TNF) alpha and Interferon gamma in a rat autoimmune myocarditis model, mice dermatitis model and diabetic mice." (PMID 22230247, 2012). "Thus, it will be interesting to examine whether the conjugation of NGO with anti-CD16 antibodies effectively suppresses Th2-mediated skin inflammation by increasing NK cell-derived IFNγ but decreasing Th2 cell-derived IL4." (PMID 39199350, 2024).
non-small cell lung carcinoma (84 papers, 2013 to 2025). A group of at least three distinct histological types of lung cancer, including non-small cell squamous cell carcinoma, adenocarcinoma, and large cell carcinoma. "These pathways include neutrophil-mediated immunity and response to interferon-gamma, suggesting that immune dysregulation is causally involved in the aetiology of non-small cell lung cancer." (PMID 38589970, 2024). "A recent study reported that non-small cell lung cancer showing a complete pathological response to immunotherapy exhibits a stronger immune infiltrate, characterized by higher levels of IFNG, GZMB, NKG7, and M1 macrophages." (PMID 39888994, 2025). "IFNγ mediates the activation of the AKT-mTOR signaling pathway in non-small cell lung cancer, increasing its PD-L1 expression." (PMID 40297576, 2025). "Increased IFNγ levels after ICI treatment were strongly associated with better patient response and survival in non-small cell lung cancer." (PMID 38026978, 2023). "It was shown to downregulate IFNγ-induced MHC-I expression in non-small cell lung cancer cell lines, and CD80/CD86 in dendritic cells stimulated with lipopolysaccharide, thereby reducing T-cell stimulatory capacity." (PMID 35655783, 2022). "Similar results were observed during a phase II trial treating inoperable non-small cell lung cancer (NSCLC) patients with DC-derived exosomes from IFNγ-matured moDCs as maintenance therapy after induction chemotherapy." (PMID 34054844, 2021). "Interferon gamma messenger RNA signature in tumor biopsies predicts outcomes in patients with non-small cell lung carcinoma or urothelial cancer treated with durvalumab." (PMID 33268350, 2020). "Similarly, it was reported that NSCLC patients with non-small cell lung cancer (NSCLC) who exhibit elevated baseline levels of interferon-gamma (IFN-γ) in their peripheral blood exhibit prolonged progression-free survival (PFS) upon treatment with PD-1 inhibitors." (PMID 40075727, 2025). "T-effector/IFNγ signature, a 8-gene signature reflecting preexisting immunity, is in phase II trial on previously treated non-small cell lung carcinoma (NSCLC)." (PMID 33049716, 2020). "Responsiveness to IFNγ and induction of MHC II expression was assessed after various treatment conditions in mouse and human non-small cell lung cancer (NSCLC) cell lines using mass cytometric and flow cytometric analysis." (PMID 32312906, 2020). "However, in a recent phase II clinical trial in non-small cell lung cancer (NSCLC), exosomes derived from DCs matured by interferon-gamma and loaded with MHC class I- and class II-restricted cancer antigens did not meet the primary endpoint of 50% non‐progressors by post‐chemotherapy." (PMID 39698504, 2021). "It has been reported that unfractionated self-peripheral blood mononuclear cells (PBMC) can be co-cultured for a long time with epithelial cell organoids from CRC or non-small cell lung carcinoma (NSCLC) in the presence of IL2, IFNγ, anti-CD3 and anti-CD28 antibodies coated to plastic for 28 days." (PMID 34298630, 2021). "In addition, PD-L1 was key in mediating IFNγ regulation of glucose and glutamine metabolism, although not through transcriptional regulation of metabolic enzymes and unlike a report of PD-L1 regulating HK2 in non-small cell lung cancer." (PMID 35656514, 2022).
ulcerative colitis (84 papers, 2009 to 2025). An inflammatory bowel disease involving the mucosal surface of the large intestine and rectum. "ILC1 secrete interferon gamma and are associated with Crohn’s disease and ulcerative colitis, possibly contributing to sustained inflammation and carcinogenesis." (PMID 38892375, 2024). "In conclusion, we have shown that urinary potassium level is inversely associated with the disease activity in ulcerative colitis and in vitro data suggests that it suppresses inflammation by reducing the IL-17 and IFNγ and inducing the Foxp3 expression on Th17 cells." (PMID 29273710, 2017). "Due to the critical role of macrophages in the inflammatory process, this study utilized LPS/IFNγ-stimulated RAW264.7 macrophages to establish an in vitro model of ulcerative colitis (UC) and evaluated the anti-inflammatory effects of DEH in vitro." (PMID 40468178, 2025). "Furthermore, methylation level at the IFNG locus is correlated with the immune response to microbial components and with the expression of IFN-γ in ulcerative colitis patients." (PMID 26287240, 2015). "The identification of TLR2, IFNG, and CD163 as hub genes suggests their potential utility as predictive biomarkers for ulcerative colitis diagnosis and disease monitoring." (PMID 41300749, 2025).
allergic asthma (83 papers, 2008 to 2025). A asthma with a basis in a pathological type I hypersensitivity reaction. "Specifically, IFNG, IL-13, IL-5, and IL-4R showed an especially high overall relationship with allergic conditions (respiratory allergy and allergic asthma)." (PMID 33936056, 2021). "We have demonstrated that in a cohort of children and adults with allergic asthma, age and sex are important predictors of IFNγ promoter DNA methylation." (PMID 24891923, 2014). "The role of IFNγ in the suppression of allergic asthma has been reported by others." (PMID 31611876, 2019). "We hypothesized age and sex-related differences exist in DNA methylation of the allergy counter-regulatory gene IFNγ in a cohort of children and adults with allergic asthma." (PMID 24891923, 2014). "On the other hand, some cytokines are negative regulators of eosinophil differentiation; for example, IL-12 selectively inhibits eosinophilopoiesis from bone marrow stem cells through IFNγ induction, reinforcing the importance of the T-helper type 1 versus T-helper type 2 balance in allergic asthma." (PMID 25204389, 2014). "Moreover, although TNFα is elevated in allergic asthma, the expression of IFNs is usually impaired, and the TNFα plus IFNγ-induced PANoptosis may be limited in normal allergic asthma." (PMID 37895022, 2023). "GA-B suppresses the production of IL-5 by inhibiting GATA3 while maintaining the expression of Foxp-3 and T-bet genes, enhancing the levels of IL-10 and Interferon gamma (IFN-γ), thus reducing the incidence of allergic asthma." (PMID 39459639, 2024). "Due to their substantial role in development of type 2 immune responses in allergic asthma, it is surprising that ST2+ILC have the ability to produce IFNγ in response to IL-33 in healthy individuals." (PMID 30174671, 2018). "CpG promoter loci of allergic asthma genes (e.g., interleukin 4 (IL4), interferon gamma (IFNγ), inducible nitric oxide synthase (NOS2A)), arginase 2 (ARG2)) were pyrosequenced at the start and end of each sampling period." (PMID 28588744, 2017). "Considering the effects of IL-7 and IFNγ, and that the hippocampus is a major neurogenic niche in the developing brain, future studies may benefit from investigating the potential for hippocampal overgrowth in offspring brains in response to UIS or allergic asthma inflammation during pregnancy." (PMID 37919762, 2023). "IL17A, IL33, and IFNγ levels were significantly elevated in allergic and nonallergic asthmatics when compared to control, whereas IL5 levels were elevated only in patients with allergic asthma when compared to control." (PMID 30306094, 2018).